LTBR (lymphotoxin beta receptor)
Diseases named in the same sentence as LTBR in open-access papers (continued):
Sharing a sentence is not in itself a finding about the gene and the disease.
tumor (106 papers, 2007 to 2026). "We further explore LTβR's interactions with key immune subsets-myeloid-derived suppressor cells (MDSCs), dendritic cells (DCs), and tumor-associated macrophages (TAMs)-and its synergy with ICB and CAR T cell therapies." (PMID 41716391, 2026). "The lymphotoxin β-receptor (LTBR) has been identified as a potential immune checkpoint in tumor-associated macrophages (TAMs)." (PMID 40034694, 2025). "Through integrative analysis of immune multiomics data and single‐cell RNA‐seq data, this study identifies lymphotoxin β receptor (LTBR) as a potential immune checkpoint of tumor‐associated macrophages (TAMs)." (PMID 39429877, 2024). "This is in contrast to a recent study which showed LTβR agonist treatment alone to be sufficient in inducing TA-HEVs which were associated with the presence of T and B cells as well as a reduction in tumor weight." (PMID 36704666, 2022). "LIGHT-LTβR interaction was found to be the principle driver for this therapy due to the complete loss of anti-tumor effects when an anti-LTβR Ig was included." (PMID 32499782, 2020). "AKT/CAT-transformation of hepatocytes and subsequent LTβ/LTβR upregulation are thus implicated in tumour proliferation and progression." (PMID 26206664, 2016). "Moreover, the transfer of CD45+ EPCs from cachexic HCC mice intravenously to tumour‐free mice caused a decrease in thymocytes compared to mFbs, decreased the mFb/capFb ratio and decreased Mmp9, LtβR and Ccl19 expression in mFbs." (PMID 40665793, 2025). "In addition, we analyzed the role of LTBR in DNA methylation, mutational status, tumor mutation burden (TMB), and microsatellite instability (MSI)." (PMID 38175686, 2024). "Previous studies using LTβR-/- and LTα-/- mice or WT mice treated with LTβR-Ig demonstrated loss of NK cell populations in the spleen, lung, blood and bone marrow as well as impairment of NK cell anti-tumor activities." (PMID 34335629, 2021). "In addition, univariate analysis revealed that lower cytoplasmic expression levels of LTβR in tumor cells of stage II patients were associated with decreased five-year OS (p = 0.008)." (PMID 31137630, 2019). "Furthermore, silencing LTβR using specific short hairpin RNA was reported to reduce the ability of perforin-deficient CTLs to induce tumor rejection in vivo." (PMID 22389673, 2012). "Depending on context and activation mode, LTβR can drive either tumor progression or anti-tumor immunity." (PMID 41716391, 2026). "Then, it is revealed that Plac1+ tumor cells recruit CD4+ T cells via CXCL11/CXCR3 and induce Treg differentiation via PVR/TIGIT, which in turn activates the tumorigenic signaling of Plac1+ tumor cells via LTA/LTBR and forms a reciprocal protumor loop." (PMID 40056047, 2025). "Results from coculture and cell transfer assays suggest that cancer cachexic CD45+ erythroid progenitor cells (EPCs) induce the death of CD34+ progenitor cells and decrease the number of LtβR+, Mmp9+ and Ccl19+ mFbs in tumour‐free mice." (PMID 40665793, 2025). "The measurement of the biological activity of soluble recombinant human LIGHT has relied so far on the use of human tumor cell lines expressing either LTβR and/or HVEM, or primary T cells expressing HVEM that can proliferate in response to LIGHT." (PMID 40457031, 2025). "LIGHT engages two key receptors, HVEM (Herpesvirus Entry Mediator) and LTβR (Lymphotoxin Beta Receptor), to stimulate T cell proliferation, activation, and recruitment within the tumor microenvironment (TME)." (PMID 40496862, 2025). "Our results suggest that one advantage of combination therapy over LTβR monotherapy is the activation and maturation of tumor-infiltrating B cells." (PMID 40897896, 2025). "LTA, although primarily secreted by lymphocytes, has been shown to promote tumor suppression via LTβR signaling in cancer cells." (PMID 40564222, 2025).
tumor (continued). "In contrast, LIGHT–LTβR interactions can induce apoptosis in LTβR-expressing tumor cells, suggesting a mechanism for direct, antigen-independent tumor cell killing." (PMID 41019052, 2025). "Tumor tissue analysis revealed elevated p21 levels and SA-β-Gal staining in nutlin-3a-treated LTβR KO tumors." (PMID 40883295, 2025). "In the meantime, Plac1+ tumor cells shape a Treg‐related immunosuppressive microenvironment via CXCL11/CXCR3 and PVR/TIGIT, which in turn activates the tumorigenic signaling of Plac1+ tumor cells via LTA/LTBR and forms a reciprocal protumor loop." (PMID 40056047, 2025). "When used as neoadjuvant therapy, the STING and LTβR agonist combination effectively immunized mice against the second tumor challenge, leading to long-term survival." (PMID 40897896, 2025). "The involvement of LTβ and genes responding to LTβR signaling, such as CXCL13, suggest an active role of the LTβ–LTβR pathway in tumor-associated endothelium and lymphoid organogenesis as previously reported." (PMID 40897896, 2025). "In a neoadjuvant setting, activation of STING and LTβR by their agonists effectively immunized mice against tumor recurrence, leading to long-term survival." (PMID 40897896, 2025). "From a therapeutic perspective, glycolysis inhibitors helped LTβR balance the proportion of Th17/Treg cells in PDOX model to inhibit tumor growth." (PMID 40436857, 2025). "Research has demonstrated that LTβR, typically low expressed in lymphocytes, exhibits a potent anti-tumor effect." (PMID 40436857, 2025). "Macrophage‐specific knockout of LTBR hinders tumor growth and prolongs survival time via blocking TAM immunosuppressive activity and M2 phenotype." (PMID 39429877, 2024). "Altogether, our results indicated that knockout of LTBR in TAMs inhibited tumor growth by disrupting TAM immunosuppressive activities and M2 phenotype." (PMID 39429877, 2024). "We found expression of LTβR to be consistently increased in a variety of tumor entities as compared to corresponding adjacent normal tissues." (PMID 39215104, 2024). "One group reported that lncRNA HOXA-AS3 facilitated tumor progression via activation of NF-κB pathway and targeting the miR-29a-3p and LTβR in gastric cancer." (PMID 39019995, 2024). "To evaluate the impact of LTBR+ TAMs on tumor development in vivo, we used macrophage‐specific LTBR knockout (LTBRcKO) mice." (PMID 39429877, 2024). "We therefore undertook an unbiased proteomic analysis of LTβR signaling and functionally examined the respective contributions of its different signaling arms, especially with regards to the tumor-promoting chemo-/cytokine production." (PMID 39215104, 2024). "A genome-scale screen for synthetic LTBR signaling is involved in the host response to infection, regulates the acute inflammatory response, and mediates tumor cell apoptosis." (PMID 38175686, 2024). "The findings indicated that LTBR expression was relatively consistent across different tumor cell lines." (PMID 38175686, 2024). "In contrast, LTβR agonist-treated tumours developed extensive and dense TA-HEVs which permeated into deeper parts of the tumour." (PMID 37287625, 2023). "Taken together it is clear that LTβR agonist or LIGHT monotherapy whilst sufficient in inducing TA-HEVs (in some mouse tumour models) is largely insufficient in driving effective anti-tumour immune responses." (PMID 37287625, 2023). "There is therefore a clear rationale for targeting the LTβR signalling pathway to induce TA-HEVs in tumours for therapeutic benefit." (PMID 37287625, 2023). "Overall, this suggests that LTβR signalling which is required for maintaining functional HEVs in SLOs is dispensable in some tumour models." (PMID 37287625, 2023).
tumor (continued). "This allowed for the de-coupling of the direct anti-tumour effects of LTβR agonist from TA-HEV induction." (PMID 37287625, 2023). "LTBR (lymphotoxin β receptor) mediates apoptosis in tumor cells and activates tumorigenesis by promoting the NF-Kβ pathway." (PMID 36980828, 2023). "The addition of LTβR agonist to this combinatory therapy led to a further significant increase in TA-HEVs in both tumour models." (PMID 37287625, 2023). "LTBR is not only expressed in lymphoid cells but also in a variety of tumor types, including numerous solid tumors." (PMID 37366426, 2023). "In contrast, studies have also reported that LTBR signaling induces tumor cell apoptosis, and the overexpression of LTBR in HeLa cells triggered ligand-independent apoptosis." (PMID 35563525, 2022). "LIGHT was also found to have direct pro-apoptotic effects on some tumor cells through the lymphotoxin-beta receptor and also by potentially releasing tumor neo-antigens." (PMID 35053501, 2022). "After LTβR agonist treatment both Treg-replete and -depleted tumors developed PNAd+ vessels that were mostly localized to the outer regions of the whole tumor." (PMID 36704666, 2022). "Other studies have shown that LTBR signaling is involved in tumorigenesis, and LTBR has been considered as a target for anti-tumor therapy." (PMID 35563525, 2022). "We found that transcripts of LTB and its receptor LTBR are found in adjacent tumor regions with overlaps at the intercept of these regions." (PMID 36230839, 2022). "Both LTβR- and RORγt+ LTα-deficient mice developed more tumors as compared with co-housed littermate control mice, clearly implicating the key role of LTαβ–LTβR signaling in tumor control." (PMID 33917839, 2021). "Another strategy makes use of the tumor vasculature normalization aspect of the tumor necrosis factor superfamily member 14 (TNFSF14/CD258/LIGHT)/lymphotoxin-β receptor (LTβR) signaling axis coupled with its intrinsic ability to turn a “cold” tumor “hot”." (PMID 34359588, 2021). "LTBR functions as a potential anti-tumor role by triggering apoptosis of tumor cells or by eliciting anti-tumor immune response." (PMID 34537809, 2021). "This highlights the importance of LTβR signaling for TLS combination immune therapies but also the potential involvement of other pathways since LIGHT activates cells within the tumor microenvironment through multiple receptors including LTβR and HVEM." (PMID 34122434, 2021). "LIGHT/LTβR signaling normalizes tumor vasculature via LTβR-dependent ICAM, vascular cell adhesion protein (VCAM), and smooth muscle actin (SMA) expression, and it facilitates infiltration of immune effector cells." (PMID 34359588, 2021). "Targeting the extracellular ectodomain of LTβR with agonistic LTβR mAbs was also employed to activate LTβR signaling to suppress tumor growth and enhance tumor chemosensitivity." (PMID 33805271, 2021). "Treatment with a LTβR-stimulating antibody partially restored the occurrence of HECs (PNAd+ BECs) in tumor-bearing LNs and substantially improved immigration of naive T cells to a level similar as observed during control conditions." (PMID 34706240, 2021). "Nevertheless, LTβR signaling can suppress colorectal cancer development via the induction of IL-22bp, the level of which is downregulated in tumor tissues from patients with CRC and correlates with a poor prognosis." (PMID 33917839, 2021). "LTB (lymphotoxin β) is a tumor necrosis factor (TNF)-related cytokine that initiates extrinsic apoptotic cell death in tumor cells via the LTβR signaling pathway." (PMID 32513298, 2020). "As a membrane‐anchored receptor for LIGHT, previous studies have shown that HVEM is mainly expressed on T cells, DC, or NK, including tumour and normal B lymphocytes, whereas LTβR is mainly expressed in a variety of parenchyma and epithelial cells." (PMID 32881263, 2020).
tumor (continued). "Mechanistic involvement of the LIGHT receptors HVEM and LTβR was indicated by including anti-LTβR and anti-HVEM antibodies in control groups that led to the loss of the anti-tumor effects of the vector." (PMID 32499782, 2020). "On the other hand, stimulation of LTβR-dependent pathways with LIGHT or agonistic antibody against LTβR promoted T cells infiltration into tumor, restricting its growth." (PMID 31878945, 2019). "Tumor infiltration by T lymphocytes that enabled to overcome the resistance was enhanced by LTβR-activation resulting in overproduction of chemokines and adhesion molecules." (PMID 31878945, 2019). "Overexpressed LIGHT (another ligand of LTβR) in tumor cells promotes TLO formation, with enhanced T-cell mediated anti-tumor immune response." (PMID 31281318, 2019). "Administration of agonistic antibody against LTβR promotes immune cell infiltration into tumor tissues and anti-tumor immunity." (PMID 31281318, 2019). "In contrast, tumour burden in CAT/anti-LTβR and NICD/anti-LTβR-treated mice was unchanged relative to Ig control." (PMID 26206664, 2016). "Intriguingly, LTβR-mediated tumour progression was largely dependent on oncogenic AKT signalling as LTβR agonism failed to alter survival in single oncogene CAT or NICD-initiated tumour models." (PMID 26206664, 2016). "AKT/β-catenin-transfected livers displayed increased expression of LTβ and LTβR, with antagonism of LTβR signalling reducing tumour progression and enhancing survival." (PMID 26206664, 2016). "Conversely, enforced LTβR-activation of AKT/β-catenin-initiated tumours induced robust increases in proliferation and progression of hepatic tumour phenotypes in an AKT-dependent manner." (PMID 26206664, 2016). "We provide evidence that AKT/CAT combined activation can mediate the upregulation of LTβ/LTβR expression and further demonstrate LTβR signalling is a central activator during tumour development." (PMID 26206664, 2016). "Quantitative PCR revealed a mean 1.8-fold increase in LTβR in AKT/CAT-initiated tumours relative to pT3 transfected control livers." (PMID 26206664, 2016). "Similar to AKT/CAT/anti-LTβR, AKT and AKT/anti-LTβR tumours were predominantly lipogenic hepatic foci, with LTβR agonism inducing the appearance of ICC-like nodules/regions by day 90 and increasing frequency in moribund mice." (PMID 26206664, 2016). "It is induced by LTβR via NF-κB and is considered as one of the main chemoattractors for tumor-infiltrating immune cells." (PMID 23555249, 2013). "Blocking LTβR with LTβR-specific neutralizing monoclonal antibody has been reported to decrease CTL cytotoxicity against tumor cells in vitro." (PMID 22389673, 2012). "The agonistic anti-LTβR mAb, 31G4D8, has been reported to induce cell death in tumor cells in conjunction with IFN-γ." (PMID 22389673, 2012). "Lymphotoxin-α (LTα) and LTβ can be expressed by T-cells and function as a mediator of tumor cell death through the LTβR." (PMID 22389673, 2012). "In some studies, it was clearly shown that by binding LTBR with some specific or oligo-sense antibodies resulted in decreased tumor growth and increased apoptosis in tumor cells." (PMID 20673323, 2010). "In some studies, it was clearly shown that by binding LTβR with some specific or oligo-sense antibodies results in decreased tumor growth and increased apoptosis in tumor cells." (PMID 18789152, 2008). "In the present study, we found that Tregs in the TME of HNSCC could secrete LTA, interacting with its receptor LTBR on Plac1+ tumor cells and activating the downstream PI3K/AKT signaling pathway to promote HNSCC cell proliferation, migration, and invasion." (PMID 40056047, 2025). "LTβR signaling increases adhesion molecules on endothelial cells, bolstering leukocyte attachment and subsequent transmigration that is of particular importance for the recruitment of primed anti-tumor CD8 T cells stimulated in the tumor draining lymph nodes." (PMID 40457031, 2025).
tumor (continued). "In conclusion, in the Plac1+ tumor cell‐Treg interaction, Tregs could enhance the malignant characteristics of Plac1+ tumor cells through the LTA/LTBR axis and by PI3K/AKT pathway activation." (PMID 40056047, 2025). "Together, these studies indicate that LTβR activation induces the production of pro-inflammatory chemo- and cytokines and that this promotes carcinogenesis and disease progression by recruiting pro-tumorigenic immune cells to the tumor tissue." (PMID 39215104, 2024). "In addition, LTBR expression was strongly correlated with immune cells, score, cancer-related functional status, tumor stemness index, MMR genes, DNA methyltransferase, DNA methylation, mutational status, TMB, and MSI." (PMID 38175686, 2024). "In addition, LTBR signaling has been shown to affect the development of various tumors, and inhibition of its expression can have an anti-tumor effect." (PMID 38175686, 2024). "LTB is the β-chain of the heteromeric complex of surface lymphotoxin (LT), which binds to the LT-β receptor (LTBR), and ligand-receptor binding between the two activates NF-κB, affects the inflammatory microenvironment of tumors, and correlates with tumor progression." (PMID 38644411, 2024). "Moreover, it is better to use macrophage‐specific conditional LTBR knockout mice to uncover the role of LTΒR+ TAMs in other tumor models." (PMID 39429877, 2024). "The induction of TA-HEVs which are associated with improved tumour control following combined immune activation (via ICB) and administration of LTβR agonist is closely mirrored in instances of TNF superfamily member 14 (LIGHT) delivery to the tumour microenvironment." (PMID 37287625, 2023). "It is possible that the intratumoral PNAd+ vessels induced by administration of LTβR agonist Abs are distinct from those induced by Treg depletion as their presence is not linked to enhanced T-cell infiltration and control of tumor growth." (PMID 36704666, 2022). "Because signaling through the LTβR pathway has been implicated in the early development of SLOs and importantly in the formation and maintenance of HEVs, we set out to test our hypothesis by administering LTβR agonist antibodies to tumor-bearing mice." (PMID 36704666, 2022). "Such differential responses to LTβR agonist antibody treatment could be due to important differences in tumors which develop in situ versus those arising from inoculated tumor cell lines." (PMID 36704666, 2022). "Increased LTβR mRNA levels in tumor, but not in normal, tissues were associated with a worse overall survival in patients with lung adenocarcinomas." (PMID 33917839, 2021). "Different cell types express LTβR in the tumor microenvironment." (PMID 33956259, 2021). "Whether these MECA-79+ tumor blood vessels are identical to MECA-79+ TA-HEVs induced through LTβR stimulation warrants further studies, but in both instances, neogenesis of TA-HEVs correlated with a robust lymphocyte-mediated antitumor response." (PMID 33956259, 2021). "LTβR signaling plays an important role in the generation and activation of tumor HEVs." (PMID 34394083, 2021). "As LTβR is also expressed on blood endothelial cells, FRC, lung epithelial cells, and most tumor cells, it will be important to determine whether separate LTβR signaling play similar or contrasting roles in these various cell types for migration." (PMID 33805271, 2021). "LTβR is expressed by a variety of immune cells, including lymphoid tissue stromal cells, myeloid cells, monocytes, alveolar macrophages in the lung, mast cells, DCs, and most adherent primary cells and tumor cell lines." (PMID 33805271, 2021). "For example, LTBR, a gene with a negative coefficient in our model, is associated with tumor necrosis and its activation is linked to carcinogenesis." (PMID 32762727, 2020).